TJP1 (tight junction protein 1)
Diseases named in the same sentence as TJP1 in open-access papers (continued):
Sharing a sentence is not in itself a finding about the gene and the disease.
cancer (167 papers, 2008 to 2025). A tumor composed of atypical neoplastic, often pleomorphic cells that invade other tissues. "In humans, Tjp1 and Tjp2 are known to play a role in the invasion and metastasis of cancer by regulating the expression of Tjp1 and Tjp2 and causing changes in barrier function due to structural alterations in tight junctions." (PMID 38255907, 2024). "In some studies, the loss or downregulation of Tjp1 has been associated with increased tumorigenic characteristics and cancer progression." (PMID 38255907, 2024). "Furthermore, Tjp1 and Tjp2 are reported to be associated with several diseases, including cancer, autoimmune disorders, and gastrointestinal disorders." (PMID 38255907, 2024). "Additionally, deletions and mutations of TJP1 promote cancer cell proliferation." (PMID 35087173, 2022). "Tjp1 expression is capable of inhibiting cell proliferation, inducing cell cycle arrest, and promoting apoptosis in cancer cells." (PMID 38255907, 2024). "In conclusion, Tjp1 and Tjp2 play a significant role in cell proliferation, migration, cancer growth, and metastasis, involving various genes." (PMID 38255907, 2024). "TJP1 is downregulated in many cancer types and low expression of TJP1 correlates with advanced stage and poor prognosis." (PMID 37790849, 2023). "Our findings are consistent with a recent publication showing that TWIST1 interacts with tight junction protein 1 (TJP1) along the cell membrane of two different cancer cells." (PMID 35781329, 2022). "Altered expression of TJP1 is found in many cancers and is responsible for modulating cancer migration and invasion." (PMID 35087173, 2022). "TJP1 expression in cancer tissues was classified into two groups (low and high) base on cutoff point, which was set at the median." (PMID 35087173, 2022). "Using bioinformatics analysis, we further found that the tight junction proteins TJP1 and TJP2 show significant positive correlations with SPIN4 and are linked to cancer cell survival." (PMID 34575061, 2021). "TJP1 may play a role in cancer progression, since the delocalization of this protein into cytoplasmic or nuclear compartments confers invasive and pro-tumorigenic functions." (PMID 38994952, 2024). "Dysregulation of TJP1 expression has been observed in various cancer types." (PMID 37790849, 2023). "In order to evaluate the effect of RNase A on metastasis development, we investigated the expression of markers associated with epithelial–mesenchymal transition (EMT): Cdh1 (E-cadherin), Tjp1, Fn and Vim (vimentin), which play important roles in cancer invasion and metastasis." (PMID 35745743, 2022). "Our data showed that TJP1 is upregulated in multiple cancer cell lines." (PMID 35087173, 2022). "Moreover, vesicular miR-23a and miR-105 were shown to inhibit the tight junction protein ZO-1 (TJP1), thereby increasing vascular permeability and cancer migration of lung and metastatic breast cancers." (PMID 30872568, 2019). "In accordance with FN1 and TJP1 roles in aggressive metastatic cancer cells, the former promotes and the latter suppresses the cancer cell aggression, western blotting demonstrated that FN1 was positively regulated and TJP1 was negatively regulated by TFCP2 in human HCC cells." (PMID 25609232, 2015). "Therefore, although it is difficult to make a generalized statement, in certain cancer types, the knockout of Tjp1 may indeed lead to an increase in tumorigenic characteristics and cancer progression." (PMID 38255907, 2024). "As EMT is a common process that has been postulated to be responsible for carcinoma cell metastasis, the effect of the BCSC secretome on the expression of epithelial markers (CDH1, TJP1 and OCLN) and mesenchymal markers (Snail, FN1, MMP2 and VIM) was assessed." (PMID 36915147, 2023). "Next, by examining the DNA copy numbers of the TJP family in multiple cancer cell lines, we observed that the DNA copy numbers of TJP1, TJP2, and TJP3 were upregulated in 10, 9, and 7 different cancer cell lines, respectively." (PMID 35087173, 2022).
cancer (continued). "By evaluating the mRNA expression of TJP1, TJP2, and TJP3 in 40 different cancer cell lines, we found that TJP1, TJP2, and TJP3 were upregulated in 29, 40, and 12 different cancer cell types, respectively." (PMID 35087173, 2022). "Consistent with this hypothesis, in ARIH1 miniTurboID experiments we detect several interacting proteins with a role in EMT modulation and cancer progression, including TJP1 (ZO1), CYLD, and UPF1." (PMID 35102251, 2022). "Although the statistical result is not significant, the increasing TJP1 in cancer tissues still positively correlate with circSMC3 expression and negatively correlate with miR‐4720‐3p expression." (PMID 32314520, 2020). "Furthermore, Twist1 expression positively correlates with EMT genes (CDH1, OCLN, TJP1, CDH2, FN1, SNAI1 and VIM) in various cancers." (PMID 32337580, 2020).
intestinal diseases (8 papers, 2018 to 2025). "Increased intestinal permeability is associated with the pathogenesis of intestinal diseases and a reduction in the ZO-1 protein encoded by Tjp1." (PMID 40431255, 2025).
neurological disease (7 papers, 2016 to 2025). "Tjp1-KO is lethal, and disruption has been linked to neurological disorders." (PMID 31906086, 2019).
adenocarcinoma (6 papers, 2013 to 2024). A common cancer characterized by the presence of malignant glandular cells. "Indole promoted mRNA expression of TJ-associated molecules, such as Cldn7, Ocln, and Tjp1 in the human adenocarcinoma cell line, Caco-2." (PMID 24278294, 2013). "In contrast to our observations, the TJP-1 protein was found to be highly expressed in adenocarcinoma samples compared to healthy tissues." (PMID 38255907, 2024).
TJP1 also shares sentences with these, for which no sentence is quoted: Sepsis (55 papers); ischemic stroke (38); ischemia (35); Cerebral ischemia (29); asthma (18); inflammation (18); viral infection (16); bacterial infection (15); cerebral infarction (13); E. coli infection (13); enteritis (12); Hepatic steatosis (12); periodontitis (11); prostate carcinoma (11); brain injury (10); diabetic retinopathy (10); irritable bowel syndrome (10); liver cancer (10); chronic kidney disease (9); cyst (9); ZIKV infection (9); Alzheimer disease (8); atherosclerosis (8); brain tumors (8); COVID-19 (8); Crohn disease (8); Hypertension (8); mastitis (8); metabolic disease (8); pulmonary edema (8).
A further 292 diseases each share a sentence with TJP1 in 8 papers or fewer.